ZNF350 (zinc finger protein 350)
Description:
Transcriptional repressor. Binds to a specific sequence, 5'-GGGxxxCAGxxxTTT-3', within GADD45 intron 3.
Synonyms: ZBRK1; ZFQR
Tractability: No criterion of Open Targets' tractability assessment is met for any kind of drug.
Gene: Protein-coding gene on chromosome 19 (51,964,061 to 51,986,856, reverse strand). Ensembl gene ENSG00000256683.
Subcellular location: Nucleus; Nucleus matrix
Subcellular location (Human Protein Atlas): Nucleoplasm; Nuclear bodies
Pathways (Reactome):
Gene expression (Transcription): Generic Transcription Pathway
Metabolism of proteins: SUMOylation of transcription cofactors
Gene Ontology:
Molecular function: DNA binding; DNA-binding transcription repressor activity, RNA polymerase II-specific; protein binding; RNA polymerase II intronic transcription regulatory region sequence-specific DNA binding; DNA-binding transcription factor activity; RNA polymerase II cis-regulatory region sequence-specific DNA binding; sequence-specific double-stranded DNA binding
Biological process: negative regulation of DNA-templated transcription; negative regulation of transcription by RNA polymerase II; regulation of DNA-templated transcription; regulation of transcription by RNA polymerase II
Cellular component: nuclear body; nucleoplasm; nucleus; transcription repressor complex; nuclear matrix
Genetic constraint (gnomAD): Loss-of-function variants: 5 observed, 14.24 expected, observed/expected ratio (o/e) 0.35, 90% interval 0.18 to 0.74. The upper end of that interval is the gene's LOEUF score, 0.74, which puts it in group 3 of 6, group 1 being the genes least tolerant of losing a copy. Missense variants: 534 observed, 675.76 expected, observed/expected ratio (o/e) 0.79, 90% interval 0.74 to 0.85. Synonymous variants: 199 observed, 235.84 expected, observed/expected ratio (o/e) 0.84, 90% interval 0.75 to 0.95.
Homologues: Orthologues: chimpanzee ZNF350 (98% identical), macaque ZNF350 (95% identical), guinea pig ZNF350 (65% identical), rabbit ZNF350 (65% identical), Drosophila melanogaster CG14442 (7% identical), Drosophila melanogaster CG14440 (4% identical). Paralogues in human: ZNF613 (63% identical), ZNF649 (55% identical), ZNF567 (40% identical), ZNF382 (37% identical), ZNF564 (29% identical), IKZF1 (16% identical), IKZF4 (15% identical), IKZF3 (15% identical), ZNF639 (14% identical), IKZF2 (14% identical), ZNF821 (10% identical).
Diseases named in the same sentence as ZNF350 in open-access papers:
ZNF350 is named in the same sentence as 24 diseases in open-access papers, as found by Europe PMC text mining. Sharing a sentence is not in itself a finding about the gene and the disease. The quoted sentences say what the papers report.
breast carcinoma (10 papers, 2011 to 2024). "In this study, the correlation between ZBRK1/ZNF350 exonic variant and breast cancer was investigated." (PMID 33407485, 2021). "We have conducted the first meta-analysis summarizing the evidence regarding the association between the five ZNF350 SNPs and the risks of developing breast cancer." (PMID 29291027, 2017). "Accordingly, ZBRK1/ZNF350 has been considered to be a new breast cancer susceptibility gene." (PMID 33407485, 2021). "The rs138898320 CT mutation genotype of ZBRK1/ZNF350 may reduce the risk of breast cancer, and the protecting effect would be increased in the stratification with no family history." (PMID 33407485, 2021). "Four studies of five distinct populations involving 5824 breast cancer cases were used to conduct a meta-analysis that summarizes the current evidence of 5 genetic polymorphisms: Asp35Asp, Leu66Pro, Pro373Pro, Ser472Pro, and Ser501Arg in the ZNF350 gene." (PMID 29291027, 2017). "In this study, through the direct sequencing of the exon region of the ZBRK1/ZNF350 gene in 80 cases of early-onset (30–40 years old) breast cancer who were admitted to our hospital, a total of 9 sequence variants were detected." (PMID 33407485, 2021). "The ZBRK1/ZNF350 gene exon detection analysis was performed with the direct sequencing and Snapshot methods in 80 cases of breast cancer (aged ≤ 40 years old) and 240 healthy subjects (aged ≤ 40 years old)." (PMID 33407485, 2021). "This study is to explore the relationship between the ZBRK1/ZNF350 (Zinc finger and BRCA1-interacting protein with KRAB domain-1; also known as zinc-finger protein 350) gene polymorphism and early-onset breast cancer." (PMID 33407485, 2021). "In conclusion, the pooled results of our meta-analysis studying We propose to that both future large-scale clinical studies and functional studies are needed to elucidate the role to which ZNF350 modify the risks of breast cancer." (PMID 29291027, 2017). "Moreover, abnormal ZBRK1/ZNF350 gene expression levels have also been observed in human breast cancer tissues." (PMID 33407485, 2021). "The BRCA1/ZBRK1 complex may play a role in the aspartic acid metabolism, and the ZBRK1/ZNF350 gene mutations have been detected in both familial and sporadic breast cancer patients." (PMID 33407485, 2021). "Some studies have reported an association between the zinc-finger protein 350 (ZNF350), also known as zinc-finger and BRCA1-interacting protein with a Kruppel-associated box (KRAB) domain (ZBRK1), and risks of breast cancer, although the results remain controversial." (PMID 29291027, 2017). "In the American population, compared to the wild-type homozygous genotype, heterozygotes at the ZBRK1/ZNF350 rs4986771 locus would suffer from increased risk of breast cancer, and the same genotype does not have significantly increased risk in the Polish population." (PMID 33407485, 2021). "ZNF350, a transcriptional suppressor, binds to BRCA1 and CtIP to form a transcriptional suppressor complex that inhibits angiogenesis in breast cancer." (PMID 38049396, 2023).
cervical carcinoma (8 papers, 2013 to 2023). A carcinoma arising from either the exocervical squamous epithelium or the endocervical glandular epithelium. "For example, ZNF350 inhibits cervical cancer progression by directly binding to the MMP9 promoter region and inhibiting its transcription." (PMID 38049396, 2023). "In cervical cancer, increased ZNF350 gene expression is correlated with inhibition of growth and metastasis of tumor cells." (PMID 30613364, 2018). "ZNF350 is also known to inhibit cervical carcinoma metastasis, perhaps via modulation of MMP9 and KAP1 expression." (PMID 30613364, 2018). "On the other hand, other studies have shown that overexpression of ZNF350 significantly impaired the migration of tumor cells in colorectal cancer and inhibited growth and metastatic activity in cervical cancer, acting as a potent tumor suppressor in different types of cancer." (PMID 36553064, 2022). "ZNF350, also known as zinc-finger and BRCA1-interacting protein with a Kruppel-associated box (KRAB) domain (ZBRK1), is involved in the development of several human tumor types, including breast, colon, and cervical carcinomas." (PMID 30613364, 2018). "In cervical cancer, increased ZNF350 gene expression is correlated with inhibition of growth and metastasis of cervical tumour cells, suggesting that ZNF350 could possibly be a tumour suppressor." (PMID 29291027, 2017).
colon cancer (4 papers, 2018 to 2024). "The methylation of the ZNF350 transcription factor’s promoter region, which causes its downregulation, is known to stimulate colon cancer cell migration." (PMID 38438786, 2024). "Consistent with this previous work, we found that colon cancer tissues had significantly reduced ZNF350 mRNA levels compared to the surrounding normal colon tissues." (PMID 30613364, 2018). "We found the hyper-methylation of the ZNF350 promoter and further showed that it significantly affects the characteristics of the colon cancer cells, especially migration." (PMID 30613364, 2018). "In addition, a previous study reported that overexpression of ZNF350 in colon cancer cells significantly increased their proliferative and migratory abilities." (PMID 36803971, 2023). "We show here that hyper-methylation of the ZNF350 promoter may be one of the crucial determinants for acquiring increased migratory capabilities in colon cancer cells." (PMID 30613364, 2018). "While further studies are needed to fully understand the potential role of ZNF350 promoter methylation in the process of colon cancer metastasis, the present study enhances our understanding of heterogeneous cell populations during carcinogenesis and highlights an essential role for DNA methylation." (PMID 30613364, 2018). "Taken together, our results suggest that hyper-methylation of the ZNF350 proximal promoter may be one of the crucial determinants for acquiring increased migratory capabilities in colon cancer cells." (PMID 30613364, 2018). "In addition, a web-based software, MethHC, showed that all four CpG sites of ZNF350 promoter were significantly hyper-methylated in colon cancer tissues compared with normal tissues." (PMID 30613364, 2018). "Thus, methylation of the ZNF350 promoter may be one of the crucial determinants for the acquisition of motility during colon cancer pathogenesis." (PMID 30613364, 2018). "Interestingly, ZNF350 tends to be underexpressed in colon cancers." (PMID 30613364, 2018). "At present, however, we can not conclude that ZNF350 is a key regulator for motility of colon cancer cells." (PMID 30613364, 2018).
colorectal cancer (3 papers, 2018 to 2024). A primary or metastatic malignant neoplasm that affects the colon or rectum. "We found that the most significant drivers of the differences between left-sided and right-sided colorectal cancer found in our analysis are ZNF350 (t-test, FDR = 0.024) and NFKB2 (t-test, FDR = 0.032) respectively." (PMID 38438786, 2024). "Although further studies are needed to figure out how ZNF350 works with BRAC1 complex to repress migration, our results suggest that ZNF350 could also be a potential tumor suppressor in different types of cancers, including colorectal cancer." (PMID 30613364, 2018).
renal carcinoma (3 papers, 2015 to 2021). A carcinoma arising from the epithelium of the renal parenchyma or the renal pelvis. "Other genes were also increased in GC tissues, for example, ZNF350 (ZBRK1) was upregulated in GC tissues, and it was reported that ZNF350 could activate VHL gene transcription through formation of a complex with VHL and p300 in renal cancer." (PMID 34594359, 2021).
glioma (2 papers, 2023 to 2025). A benign or malignant brain and spinal cord tumor that arises from glial cells (astrocytes, oligodendrocytes, ependymal cells). "Survival analysis involving a large number of glioma samples revealed that ZNF350 low expression group had higher survival rate." (PMID 38049396, 2023). "HECW1 and ZNF350 are involved in the biological processes of many tumors, but their specific effects and mechanisms on glioma are still unclear." (PMID 38049396, 2023). "In summary, this study is the first to reveal the influence of HECW1 and ZNF350 on gliomas and their potential value in evaluating patient prognosis." (PMID 38049396, 2023). "We demonstrate that HECW1 induces ferroptosis and highlight the value of HECW1 and ZNF350 in the prognostic evaluation of patients with glioma." (PMID 38049396, 2023). "In this study, we found that HECW1 decreased the survival rate of glioma cells and enhanced iron accumulation, lipid peroxidation, whereas ZNF350 showed the opposite effect." (PMID 38049396, 2023). "In this study, we found that ZNF350 was upregulated in gliomas and predicted a shorter survival time in patients." (PMID 38049396, 2023). "Our experiments also showed that ZNF350 overexpression promoted glioma cell viability and inhibited cell death." (PMID 38049396, 2023). "We also confirmed that ZNF350 not only promotes glioma cell proliferation, migration, invasion, and activity but also reduces cell death." (PMID 38049396, 2023). "Similarly, ZNF350 expression was significantly higher in glioma tissues than in normal brain tissues and higher in HGGTs than in LGGTs." (PMID 38049396, 2023). "The main reason for this phenomenon was ferroptosis inhibition by ZNF350 in glioma cells." (PMID 38049396, 2023). "Protein levels of both ZNF350 and JUND were upregulated in HECW1-deficient glioma cells." (PMID 38049396, 2023). "Taken together, we confirmed that HECW1, ZNF350, and NCOA4 form an integral pathway involved in the regulation of ferroptosis in gliomas." (PMID 38049396, 2023). "More importantly, we explore and demonstrate the role and mechanism of the HECW1/ZNF350/NCOA4 pathway in regulating ferroptosis and identify new molecular targets for glioma therapy." (PMID 38049396, 2023). "For instance, ZNF350 enhances ferroptosis in glioma cells by reducing transcriptional repression of NCOA4, thereby promoting glioma progression, elevating STING levels to increase NCOA4 binding, enhancing ferroptosis in renal tubular epithelial cells, and exacerbating acute kidney injury." (PMID 40374601, 2025). "Here, we demonstrated the regulatory mechanism of the HECW1/ZNF350/NCOA4 pathway on ferroptosis in gliomas, which might provide a novel strategy for glioma treatment." (PMID 38049396, 2023). "In addition, we demonstrated that ZNF350 overexpression reversed the HECW1-induced accumulation of MDA, ROS, and Fe2+ in glioma cells." (PMID 38049396, 2023). "As a transcription factor, ZNF350 did not affect HECW1 expression in glioma cells." (PMID 38049396, 2023). "However, the potential effect and mechanism of ZNF350 in glioma have not yet been clarified." (PMID 38049396, 2023).
ovarian carcinoma (2 papers, 2011 to 2024). A malignant neoplasm originating from the surface ovarian epithelium. "Genetic variants and haplotype analyses of the ZNF350 (ranked at 12) gene suggested that it is associated with high-risk non BRCA1/2 French Canadian breast and ovarian cancer families." (PMID 21799737, 2011).
breast tumor (1 paper, 2018). "A possible mechanism is that the ZNF350/BRCA1/CtTB-interacting protein complex represses the expression of angiopoietin-1 (ANG1) and high-mobility group AT-hook 2 (HMGA2), which are commonly involved in the proliferation and vascularization during breast tumor formation." (PMID 30613364, 2018).
kidney cancer (1 paper, 2021). Primary or metastatic malignant neoplasm involving the kidney. "An increasing number of reports reveal the role of ZNF350 (ZBRK1) in suppressing the progression of distinct types of solid tumors, including cervical, breast, and kidney cancers." (PMID 34638319, 2021).
kidney tumors (1 paper, 2021). "In our data, ZNF350 expression is significantly negatively correlated with cancer stemness and is associated with the better overall survival of KIRC patients, suggesting its tumor-suppressive role in kidney tumors." (PMID 34638319, 2021).
tumor (14 papers, 2013 to 2025). "ZNF350, also known as zinc-finger and BRCA1-interacting protein with a Kruppel-associated box (KRAB) domain (ZBRK1), have been shown to be involved in the pathogenic developments of several human tumours, such as breast, colon, and cervical carcinogenesis." (PMID 29291027, 2017). "Based on these data, we were particularly interested in ZNF350 encoding zinc finger protein 350 (ZNF350/ZBRK1) that has been suggested to function as a tumor suppressor, namely repression of metastasis/invasion, via interaction with breast cancer 1 (BRCA1) and KRAB-ZFP-associated protein 1 (KAP1)." (PMID 30613364, 2018). "In each case we confirm the profile observed, with TLL1 and ZNF350 being more methylated in the tumour than placenta." (PMID 31357948, 2019). "ZNF350 is a transcriptional repressor that has been suggested as a tumor suppressor due to its close corporation with BRCA1 and KAP-1 to silence DNA damage response genes." (PMID 29291027, 2017). "Zinc Finger Protein 350 (ZNF350) regulates tumor growth, metastasis, and inflammation." (PMID 41440381, 2025). "Therefore, the sequence variation of the ZBRK1/ZNF350 gene is likely to affect the interaction between its product and BRCA1, thus interfering with the function of the tumor suppressor." (PMID 33407485, 2021).
cancer (9 papers, 2013 to 2025). A tumor composed of atypical neoplastic, often pleomorphic cells that invade other tissues. "Similarly, we identified 57 potential TSGs, of which at least 13 have been implicated in cancer, including HOXB13, ZNF350, ZNF331, CNTNAP2, NEFH, and ABR with reduced expression due to hypermethylation or loss." (PMID 37245006, 2023). "Our genome-wide analyses of DNA methylation and gene expression profiles identified ZNF350 as a DNA methylation-dependent regulator, which may determine a cancer phenotype among heterogeneous subpopulation." (PMID 30613364, 2018). "Considering the possible role of ZNF350, one might speculate that the larger cancer and more advanced cancer should show lower levels of ZNF350." (PMID 30613364, 2018).
ZNF350 also shares sentences with these, for which no sentence is quoted: acute kidney injury (1 paper); bladder cancer (1); cervical tumour (1); chronic hepatitis B (1); colon adenocarcinoma (1); head and neck cancer (1); in situ carcinoma (1); infection (1); metabolic syndrome (1); renal clear cell cancer (1); Temple syndrome (1); Williams syndrome (1).